SLC40A1 (solute carrier family 40 member 1)
Diseases named in the same sentence as SLC40A1 in open-access papers (continued):
Sharing a sentence is not in itself a finding about the gene and the disease.
ovarian carcinoma (22 papers, 2017 to 2026). A malignant neoplasm originating from the surface ovarian epithelium. "A reduced expression of SLC40A1 results in iron overload in ovarian cancer cells, which has been linked to cisplatin resistance." (PMID 38186569, 2023). "SLC40A1 is a novel iron metabolism associated gene and it regulates iron metabolism to overcome cisplatin resistance in ovarian cancer." (PMID 34631790, 2021). "SLC40A1, has been found to be associated with cisplatin resistance in ovarian cancer." (PMID 29212168, 2017). "In addition, SLC40A1 is associated with cisplatin resistance in ovarian cancer." (PMID 30813939, 2019). "Iron metabolism’s role extends to chemotherapy resistance, with specific alterations in the iron transporter SLC40A1 affecting cisplatin resistance in ovarian cancer cells." (PMID 39061859, 2024). "Lastly, SLC40A1 (Solute carrier family 40, member 1) is already described in ovarian cancer and multiple myeloma, where it inhibits cell growth and reduces chemotherapy resistance." (PMID 39513861, 2024). "The expression of most genes involved in iron export, including ABCG2, FLVCR1, FLVCR2, and SLC40A1, was associated with improved PFS in ovarian cancer." (PMID 38186569, 2023). "Previous studies in multiple myeloma and ovarian cancer have shown that SLC40A1 inhibits tumor cell growth and reduces resistance to chemotherapy." (PMID 36474171, 2022). "For example, miR-194-5p can induce cisplatin resistance in ovarian cancer by inhibiting the expression of SLC40A1." (PMID 34127010, 2021). "Elevated levels of Nrf2 and reduced levels of SLC40A1 were previously found in CDDP-resistant ovarian cancer cells, contradictory to our findings, indicating different iron needs and transport modification in TGCTs." (PMID 33473258, 2020). "Consistent with mRNA data, elevated protein level of Nrf2 and reduced protein level of SLC40A1 were also found in two cisplatin–resistant ovarian cancer cells." (PMID 29212168, 2017). "It was revealed that enhanced expression of SLC40A1 sensitized ovarian cancer to cisplatin and also resulted in increased expression of Nrf2." (PMID 29212168, 2017). "Elevated mRNA level of Nrf2 and reduced mRNA level of SLC40A1 were found in three cisplatin–resistant ovarian cancer cells as compared with their corresponding cisplatin-sensitive ovarian cancer cells." (PMID 29212168, 2017). "Elevated level of Nrf2 and reduced level of SLC40A1 were found in cisplatin–resistant ovarian cancer cells as compared with cisplatin-sensitive ovarian cancer cells." (PMID 29212168, 2017). "In this study, we try to confirm Nrf2’s regulation on SLC40A1, and explore the role of iron metabolism in chemoresistance in ovarian cancer." (PMID 29212168, 2017). "SLC40A1 may result in resistance to cisplatin in ovarian cancer, promote prostate cancer growth and reduce the hepatocellular carcinoma cells' ability to proliferate." (PMID 40384436, 2025). "The expression of FLVCR2 and SLC40A1 involved in iron export was associated with improved OS in ovarian cancer, while the expression of MON1A in this process was associated with poor OS in ovarian cancer." (PMID 38186569, 2023). "Iron overload induced by SLC40A1 resulted in cisplatin resistance in ovarian cancer." (PMID 29212168, 2017). "To study whether there is a relationship between Nrf2 and SLC40A1, we analyzed their mRNA expression in three cisplatin-sensitive ovarian cancer cells (A2780, COC1, PEO1) and their derived cisplatin-resistant ones (A2780CP, COC1/DDP, PEO4)." (PMID 29212168, 2017). "Moreover, in this study it showed that Nrf2 could combine to the promotor of SLC40A1 and transcriptionally suppressed the expression of SLC40A1 in ovarian cancer." (PMID 29212168, 2017). "C2 SLC40A1+ TCs and C5 CFAP126+ TCs, characterized by a significant prevalence in ovarian cancer tissues, demonstrated a low degree of differentiation, suggesting a higher malignancy in these two subtypes of TCs." (PMID 40612060, 2025).
ovarian carcinoma (continued). "Similarly, most genes involved in iron export, such as SLC40A1, FLVCR1, ABCG2, and MON1A, displayed reduced expression in ovarian cancer tissues; in contrast, only one gene, FLVCR2, showed the opposite trend." (PMID 38186569, 2023). "Similar change of SLC40A1 was found in COC1 and COC1/DDP ovarian cancer cells." (PMID 29212168, 2017).
lung carcinoma (21 papers, 2016 to 2025). "Iron management has a role in the tumorigenesis process; in some types of cancer such as breast, prostate, and lung cancer, SLC40a1 expression is decreased." (PMID 40699726, 2025). "Other miRNA target genes for ferroptosis in lung cancer cells include SLC40A1, which is regulated by MIRNA302." (PMID 34742351, 2021). "In lung cancer cell, proteasomal degradation of SLC40A1 is inhibited by ubiquitin specific peptidase 35 (USP35), which is a deubiquitinating enzyme that is abnormally expressed in many cancers." (PMID 34742351, 2021). "In the lung cancer group, PRKG2 exhibited significant positive correlation with NFE2L2, SLC40A1, TFRC, and significant negative correlation with CHAC1 and HSPB1." (PMID 39744538, 2024).
hereditary hemochromatosis (19 papers, 2013 to 2025). An inherited metabolic disorder characterized by iron accumulation in the tissues. "Hereditary hemochromatosis (HH) type 4 or ferroportin disease (OMIM-code: 606069 Orphanet-code: 139491) is associated with variants in SLC40A1 and inherited in an autosomal-dominant manner." (PMID 31505869, 2019). "Mutations in the ferroportin gene (SLC40A1) have been linked to high iron stores and haemochromatosis in humans influencing hepcidin levels." (PMID 26466783, 2015). "Mutations in SLC40A1 are associated with a form of haemochromatosis known as African Iron Overload." (PMID 34128465, 2021). "For the SLC40A1 gene, three SNPs were selected that led to alterations in iron status measures and severity of haemochromatosis." (PMID 32609760, 2020). "Genetic variants leading to excess body iron occur mainly in the haemochromatosis (HFE) gene but are also seen in hepcidin (hepcidin antimicrobial peptide (Hamp)), transferrin receptor 2 (TFR2), solute carrier family 40 member 1 (SLC40A1), haemojuvelin (HJV) and transferrin (TF) genes." (PMID 32609760, 2020). "With the increase of the reports of non-HFE hereditary hemochromatosis, more and more patients with type 4 which is associated with V162del mutation of SLC40A1 gene were diagnosed." (PMID 31689754, 2019). "A liver biopsy showed an almost normal liver specimen with a slight deposition of iron in 2-3% of hepatocytes, and a genetic examination of hereditary hemochromatosis revealed no typical mutations in HFE, TFR2, HJV, HAMP, or SLC40A1." (PMID 36968338, 2023).
hepatocellular carcinoma (15 papers, 2008 to 2025). A malignant tumor that arises from hepatocytes. "Solute carrier family 40 member 1(SLC40A1) mediates ferroptosis in diseases including diabetes, cardiac dysfunction, and hepatocellular carcinoma." (PMID 39364414, 2024). "A TAM signature expressing SLC40A1, which encodes for the iron exporter ferroportin, and GPNMB, which encodes the glycoprotein nonmetastatic melanoma protein B (NMB), was correlated with poor prognosis in hepatocellular carcinoma." (PMID 34572836, 2021).
atherosclerosis (12 papers, 2014 to 2025). A disease characterized by the build-up of fatty material and calcium deposition in the arterial wall resulting in partial or complete occlusion of the arterial lumen. "In our study, we identified APLNR, PCDH12, PODXL, SLC40A1, TM4SF18, and TNFRSF25 as the most relevant genes associated with lipid metabolism and atherosclerosis, highlighting their potential as diagnostic and immune markers." (PMID 40070840, 2025). "We determined that APLNR, PCDH12, PODXL, SLC40A1, TM4SF18, and TNFRSF25 are key genes associated with lipid metabolism in samples affected by atherosclerosis." (PMID 40070840, 2025). "Through further differential analysis and screening using machine learning algorithms, APLNR, PCDH12, PODXL, SLC40A1, TM4SF18, and TNFRSF25 were identified as key diagnostic genes for atherosclerosis." (PMID 40070840, 2025). "Investigations into the roles of ANXA2 and SLC40A1 in the pathogenesis of atherosclerosis are notably scarce." (PMID 39364414, 2024). "In our study, we utilized several machine learning algorithms to determine that LAPTM5, SLC40A1, TYROBP, CTSB, and PYCARD, which are related to macrophage genes, can act as diagnostic indicators for individuals with atherosclerosis and are linked to immune infiltration in this disease." (PMID 40881888, 2025). "Our study employed various machine learning algorithms to identify that APLNR, PCDH12, PODXL, SLC40A1, TM4SF18, and TNFRSF25, among the lipid metabolism genes, can serve as diagnostic markers in patients with atherosclerosis and are associated with atherosclerotic immune infiltration." (PMID 40070840, 2025). "Our study highlights the important roles of LAPTM5, SLC40A1, TYROBP, CTSB, and PYCARD in the context of atherosclerosis." (PMID 40881888, 2025). "The results demonstrated significantly higher expression levels of LAPTM5, SLC40A1, TYROBP, CTSB, and PYCARD in the serum of atherosclerosis patients compared to the healthy controls." (PMID 40881888, 2025). "The ROC curve was employed to assess the predictive potential of these key gene markers in atherosclerosis, revealing that the AUC values for APLNR, PCDH12, PODXL, SLC40A1, TM4SF18, and TNFRSF25 were 0.763, 0.859, 0.780, 0.807, 0.792, and 0.848, respectively." (PMID 40070840, 2025). "Through our investigation, we discerned the crucial functions of APLNR, PCDH12, PODXL, SLC40A1, TM4SF18, and TNFRSF25 within the framework of atherosclerosis." (PMID 40070840, 2025).
diabetes (10 papers, 2021 to 2025). "According to the diagnostic criteria of relevant guideline, the proband was diagnosed as SLC40A1-related HC, displaying cirrhosis, diabetes and arthropathy." (PMID 38886778, 2024). "Cases with HJV-related HH had an earlier age at diagnosis and the more severe iron load, whereas more cases with SLC40A1 HH had cirrhosis and diabetes." (PMID 34583728, 2021). "This study concludes that the ferroptosis pathway was involved in the tubule protective effect of dapagliflozin in diabetes, and the decrease in ubiquitination degradation of SLC40A1 after binding with dapagliflozin may be the mechanism underlying its action." (PMID 35993021, 2022). "In the present study, cases with SUGP2 or DENND3 HH group showed lower involvement of skin pigmentation, arthropathy, cardiac diseases, diabetes and hypogonadism, when compared to HJV HH group; and lower prevalence of cirrhosis when compared to SLC40A1 HH group." (PMID 34583728, 2021).
glioma (10 papers, 2021 to 2025). A benign or malignant brain and spinal cord tumor that arises from glial cells (astrocytes, oligodendrocytes, ependymal cells). "Survival analysis indicated that patients with high SLC40A1 expression had shorter survival times, suggesting its association with glioma malignancy and relevance to erianin and REST-related ferroptosis." (PMID 39039049, 2024). "An in silico study suggested the role of SLC40A1 as a ferroptosis suppressor, associated with immunosuppression in gliomas." (PMID 39513861, 2024). "Only one recent bioinformatics study has suggested that the ferroptosis suppressor SLC40A1 is associated with immunosuppression in gliomas and that acetaminophen may exert antitumor effects in GBM by modulating SLC40A1-induced death." (PMID 36474171, 2022). "Meanwhile, GTEX and TCGA database comparisons showed significant elevated SLC40A1 expression in glioma compared to normal brain tissue, with increased expression correlating with higher WHO grading." (PMID 39039049, 2024). "In summary, high expression of SOAT1 and SLC40A1 can reduce the level of lipid peroxidation, thereby reducing the conversion of cholesterol to cholesterol esters and inhibiting ferroptosis in glioma cells." (PMID 37980334, 2023). "In conclusion, our findings demonstrate that SOAT1 influences the sensitivity of glioma cells to ferroptosis by modulating SLC40A1." (PMID 37980334, 2023). "Inhibition of SOAT1 regulates SLC40A1 through the PI3K/AKT/mTOR pathway, elevating the level of lipid peroxidation in glioma cells and enhancing their sensitivity to ferroptosis inducers and radiotherapy." (PMID 40583858, 2025). "The mRNA level of SLC40A1 was significantly higher in glioma tissues than normal tissues in a comprehensive dataset (TCGA-GBM plus TCGA-LGG), and the expression of SLC40A1 increased with an increase in tumor grade." (PMID 37980334, 2023). "The glioma cells treated with T4O showed a significant reduction in the expression of the negative regulators of ferroptosis, GPX4, COX2, SLC40A1, and SLC7A11." (PMID 37375197, 2023). "Therefore, silencing SOAT1 may significantly reduce the survival rate of glioma cells under RT by increasing the level of lipid peroxidation, whereas SLC40A1 OE and DFO, increases the survival rate of glioma cells by reducing the level of lipid peroxidation." (PMID 37980334, 2023). "Subsequent analyses prioritized SLC40A1 over IREB2, since IREB2 has no expression or survival significance in glioma." (PMID 39039049, 2024).
glioblastoma (7 papers, 2022 to 2024). The most malignant astrocytic tumor (WHO grade IV). "In contrary, glioblastoma-mediated iron export via miR-147a-SLC40A1 (encoding FPN) axis is conducive to the elimination of ferroptosis." (PMID 39309434, 2024). "Moreover, ferroptosis suppressor SLC40A1 was significantly associated with prognosis and immunosuppression, serving as a survival predictor in glioblastoma and pancreatic cancer." (PMID 37728703, 2023). "miR-147a, induced by HIF1A, binds to the 3′-UTR of solute carrier family 40 member 1 (SLC40A1) to trigger ferroptosis in glioblastoma (U87MG) cells." (PMID 36835100, 2023). "We for the first time determine that miR-147a targets SLC40A1 to induce ferroptosis in human glioblastoma in vitro." (PMID 35942174, 2022). "In summary, our data for the first time determine that miR-147a targets SLC40A1 to induce ferroptosis in human glioblastoma in vitro." (PMID 35942174, 2022). "Accordingly, we herein demonstrated that miR-147a directly bound to the 3′-UTR of SLC40A1 and suppressed its expression, thereby promoting intracellular iron accumulation, lipid peroxidation, and ferroptosis of human glioblastoma cells in vitro." (PMID 35942174, 2022). "Taken together, we demonstrate that the miR-147a mimic elicits ferroptosis of human glioblastoma cells through targeting SLC40A1." (PMID 35942174, 2022). "In human glioblastoma, SLC40A1 was found to induce ferroptosis and affect cell viability." (PMID 37740815, 2023). "And a significant increase of SLC40A1 expression was observed in human glioblastoma tissues." (PMID 35942174, 2022).
hyperferritinemia (7 papers, 2010 to 2023). "Variants in SLC40A1 are very common in African populations, suggesting that SLC40A1 is the gene most frequently associated with hereditary hyperferritinemia in Africans." (PMID 36768886, 2023). "Of the 176 individuals reported with SLC40A1 mutations, 80 were classified as classical phenotype with hyperferritinemia and normal transferrin saturation." (PMID 20691492, 2010). "In addition, due to the increased need for phenotypic and genetic testing, rare SLC40A1 variants have been found by chance in patients with secondary causes of hyperferritinemia." (PMID 33714956, 2021). "These include hereditary hyperferritinemia cataract syndrome (HHCS) due to mutations in the IRE region of FTL, so-called benign hyperferritinemia due to mutations in the first exon of FTL, and ferroportin disease due to loss-of-function mutations of SLC40A1." (PMID 36768886, 2023). "In two patients it coexists with SLC40A1 mutations, but it was unable to modify the Ferroportin disease phenotype characterized by hyperferritinemia with normal TSAT, and in the other two patients it was associated with hyperferritinemia alone." (PMID 34828384, 2021). "More recently, in 1306 non-hemochromatosis patients with hyperferritinemia and liver iron overload, only 71 patients (5.4%) showed SLC40A1 variants, of which 10 were of unknown significance and 22 were likely pathogenic." (PMID 36768886, 2023). "Inherited isolated hyperferritinemia includes several rare or ultra-rare disorders caused by mutations in genes directly involved in iron metabolism (FTL, CP, SLC40A1) or not, such as GBA1." (PMID 36768886, 2023).
pancreatic cancer (6 papers, 2022 to 2025). "Surprisingly, expression of SLC40A1 is significantly higher in pancreatic tumors as compared to normal pancreas tissues in TCGA and GTEx databases, whereas HAMP expression is not differentially expressed in normal vs tumor pancreatic tissues." (PMID 36333531, 2022). "Through in vitro cell experiments, we clarified that Na-OHB downregulated CAV1 expression in pancreatic cancer cells, inhibiting the transcription of the CAV1/AMPK/NRF2 downstream ferroptosis-protective genes SLC7A11 and SLC40A1." (PMID 40180904, 2025). "Among the key players in iron homeostasis, solute carrier family 40 member 1 (SLC40A1, also known as ferroportin) is the only known iron exporter in mammals, pivotal for orchestrating cellular iron dynamics in ferroptotic pancreatic cancer cells." (PMID 39090114, 2024). "Moreover, SLC40A1 expression positively correlates with the expression of TAM genes (CD68, MRC1, IL10, CSF1, and CSF1R) in pancreatic tumors." (PMID 36333531, 2022).
Sepsis (6 papers, 2022 to 2026). Sepsis is defined as life-threatening organ dysfunction caused by a dysregulated host response to infection. "Neuron-specific knockdown of Slc40a1 or c-Maf deteriorated sepsis-induced cognitive impairment, oxidative stress, and ferroptosis." (PMID 41804166, 2026). "During sepsis, lactate‐dependent H3K14 lactylation at the promoter regions of ferroptosis‐related genes (TFRC, SLC40A1) promoted ferroptosis in ECs, which drives vascular dysfunction in sepsis‐related ARDS." (PMID 39822760, 2025). "Machine learning-based feature selection identified four robust biomarkers (APEX1, CTSD, SLC40A1, PIK3CB) associated with sepsis." (PMID 41041634, 2025). "A nomogram was constructed based on the expression profiles of APEX1, CTSD, SLC40A1, and PIK3CB, allowing for individualized prediction of sepsis risk." (PMID 41041634, 2025). "Our study, for the first time, discovered the regulatory effects of glycolysis‐derived H3K14la on ferroptosis in sepsis‐induced lung injury and revealed that H3K14la activated ECs by modulating the gene transcription of TFRC and SLC40A1." (PMID 39822760, 2025). "Molecular docking analysis further indicated potential interactions between α-HB and key targets (APEX1, CTSD, SLC40A1, PIK3CB), providing insights into the molecular mechanisms of α-HB in sepsis." (PMID 41041634, 2025). "Violin plots depict the differential expression of CTSD, SLC40A1, PIK3CB (upregulated), and APEX1 (downregulated) in sepsis patients compared to the control group (***p < 0.001)." (PMID 41041634, 2025). "Notably, APEX1, CTSD, SLC40A1, and PIK3CB were consistently selected by all three algorithms, underscoring their potential as robust marker genes for sepsis diagnosis and progression." (PMID 41041634, 2025).
liver fibrosis (5 papers, 2016 to 2025). "Regarding the primary objectives of the study, an association was found between genetic polymorphisms of SLC40A1 with liver fibrosis and its improvement after HCV clearance with DAAs." (PMID 41157574, 2025). "Through Cell Phone analysis, we found that C1QC and SLC40A1 macrophages were also associated with liver fibrosis and cirrhosis, which might act by interacting with NK and MAIT cells." (PMID 36845083, 2023). "No study has reported an association between SLC40A1 polymorphisms and liver fibrosis." (PMID 41157574, 2025).